NRBP2 (nuclear receptor binding protein 2)
Description:
May regulate apoptosis of neural progenitor cells during their differentiation.
Synonyms: PP9320; TRG16; DKFZp434P086
Tractability: PROTAC: ubiquitination databases record sites on it; its protein half-life has been measured.
Gene: Protein-coding gene on chromosome 8 (143,833,583 to 143,840,973, reverse strand). Ensembl gene ENSG00000185189.
Subcellular location: Cytoplasm
Subcellular location (Human Protein Atlas): Cytosol
Gene Ontology:
Molecular function: protein binding; protein serine/threonine kinase activity; ATP binding; protein kinase activity
Biological process: negative regulation of macroautophagy; DNA damage response; intracellular signal transduction; negative regulation of neuron apoptotic process; neuron differentiation; positive regulation of canonical Wnt signaling pathway; regulation of monoatomic cation transmembrane transport
Cellular component: cytoplasm; cytosol
Genetic constraint (gnomAD): Loss-of-function variants: 47 observed, 65.58 expected, observed/expected ratio (o/e) 0.72, 90% interval 0.57 to 0.91. The synonymous counts are far from expectation, so gnomAD's model fits this gene poorly and the ratio says little. Missense variants: 613 observed, 641.1 expected, observed/expected ratio (o/e) 0.96, 90% interval 0.89 to 1.02. Synonymous variants: 312 observed, 252.97 expected, observed/expected ratio (o/e) 1.23, 90% interval 1.12 to 1.36.
Homologues: Orthologues: chimpanzee NRBP2 (100% identical), mouse Nrbp2 (95% identical), rat Nrbp2 (95% identical), pig NRBP2 (93% identical), macaque NRBP2 (92% identical), dog NRBP2 (86% identical), zebrafish nrbp2b (63% identical), zebrafish nrbp2a (62% identical), tropical clawed frog puf60 (59% identical), Drosophila melanogaster Madm (49% identical), Caenorhabditis elegans hpo-11 (43% identical), Caenorhabditis elegans wnk-1 (24% identical), and 1 more. Paralogues in human: NRBP1 (60% identical), WNK2 (30% identical), WNK1 (30% identical), WNK3 (29% identical), WNK4 (27% identical), DSTYK (11% identical).
Diseases named in the same sentence as NRBP2 in open-access papers:
NRBP2 is named in the same sentence as 19 diseases in open-access papers, as found by Europe PMC text mining. Sharing a sentence is not in itself a finding about the gene and the disease. The quoted sentences say what the papers report.
breast carcinoma (4 papers, 2021 to 2024). "As for NRBP2 itself, it has recently been demonstrated as a tumor inhibitor in breast cancer since its poor expression was related to poor prognosis of patients and its high expression limited tumor metastasis." (PMID 35491849, 2022). "In our study, we clarified the role of NRBP2 in the occurrence and development of breast cancer for the first time." (PMID 33816275, 2021). "NRBP2 was expressed at lower levels in the tumor tissues than in normal tissues, and NRBP2 was related to the stage, type and lymph node metastasis of breast cancer." (PMID 33816275, 2021). "However, the role and the mechanism of NRBP2 in the regulation of the progression of breast cancer (BC) have not been reported." (PMID 33816275, 2021).
hepatocellular carcinoma (4 papers, 2020 to 2024). A malignant tumor that arises from hepatocytes. "NRBP2 is one of the pseudokinases discovered during neural differentiation gene screening, which can inhibit the progression of various cancers such as medulloblastoma and hepatocellular carcinoma." (PMID 38778371, 2024). "In addition, NRBP2 has recently been shown to increase the sensitivity of hepatocellular carcinoma cells against chemotherapy, thus suggesting a role in cancer." (PMID 32517178, 2020). "We hypothesized that NRBP2 could be endowed with tumor-reducing capacity, and base this assumption on the findings presented in this study, and a publication on hepatocellular carcinoma that suggested NRBP2 to increase sensitivity to chemotherapy." (PMID 32517178, 2020). "In addition, NRBP2 showed a chemo-sensitizing effect in hepatocellular carcinoma cells." (PMID 35491849, 2022). "Nuclear Receptor Binding Protein 2 (NRBP2), one of the pseudokinases discovered during a screen of neural differentiation genes, inhibits tumor progression in medulloblastoma and hepatocellular carcinoma." (PMID 33816275, 2021).
medulloblastoma (4 papers, 2020 to 2024). A malignant, invasive embryonal neoplasm arising from the cerebellum. "NRBP2 causes the death of NSPCs, medulloblastoma cells and HCC cells." (PMID 33816275, 2021). "In summary, the ability of NRBP2 to cause disadvantageous consequences for MB tumor cells suggest that it could be worth investigating ways to increase NRBP2 levels to target several features of medulloblastoma." (PMID 32517178, 2020). "Likewise, NRBP2 was poorly expressed in medulloblastoma and it reduced survival and growth of tumor cells upon overexpression." (PMID 35491849, 2022). "No NRBP2 mutations were revealed in the three different datasets containing a total of 243 medulloblastoma samples on cBioportal, and therefore we conclude that NRBP2 gene alterations in medulloblastoma, if they exist, are rare." (PMID 32517178, 2020). "Due to the significant down regulation of NRBP2 expression in medulloblastoma patients, we queried publicly available databases for mutations in the NRBP2 gene that might explain the difference to normal brain." (PMID 32517178, 2020). "Hence, NRBP2 expression seems to be specifically regulated by NCOR in D324 medulloblastoma cells." (PMID 32517178, 2020). "Since it has been proposed that repression of NRBP2 expression is mediated by NCOR/SMRT complexes in murine embryonic fibroblasts, we studied the effects of siRNA downregulation of individual components of this complex in D324 medulloblastoma cells." (PMID 32517178, 2020).
brain tumor (2 papers, 2020 to 2021). "To further clarify the cellular localization of NRBP2 protein in brain tumor cells, we used two MB cell lines (D283, D324), a cell line from a central nervous system (CNS) embryonal tumor (PFSK), and a glioblastoma cell culture (U3013MG)." (PMID 32517178, 2020). "Consistent with our previous finding in mouse NSPCs and the current brain tumor tissue array, NRBP2 protein, despite its’ name is mostly located in the cytoplasmic compartment." (PMID 32517178, 2020). "Here, we report that there is very little NRBP2 expression in a cohort of brain tumor patients, including MB, and through data-base mining we found that NRBP2 expression is lower in MB than in the normal cerebellum." (PMID 32517178, 2020). "To study the role of NRBP2 in brain tumors, we stained a brain tumor tissue array for NRPB2, and find its expression to be low, or absent, in a majority of the tumors." (PMID 32517178, 2020). "Therefore, we performed immunohistochemical staining of a brain tumor tissue array (TMA) with an antibody to NRBP2, followed by annotation by an experienced neuropathologist." (PMID 32517178, 2020). "Because NRBP2 expression in the mouse brain was higher in differentiated neurons and lower in stem cells, we hypothesized that it might also be expressed at low levels in brain tumor cells, since cancer cells share many properties with NSPCs." (PMID 32517178, 2020). "Nuclear Receptor Binding Protein 2 (NRBP2) is a 55–60 kDa conserved protein with a cytoplasmic localization in neural stem/progenitor cells (NSPCs), brain tumor cells and HCC cells." (PMID 33816275, 2021). "NRBP2 staining of brain tumor tissue reveals very low protein expression, and this prompted us to examine published transcriptional profiles of MB versus normal brain, where we observe a NRBP2 downregulation that distinguished MB from a non-tumor brain." (PMID 32517178, 2020).
thyroid cancer (2 papers, 2022 to 2023). "Decreased nuclear receptor-binding protein 2 (NRBP2) expression was observed in thyroid cancer (TC) tissues and cells." (PMID 36968022, 2023).
autoimmune disease (1 paper, 2025). A disorder resulting from loss of function or tissue destruction of an organ or multiple organs, arising from humoral or cellular immune responses of the individual to their own tissue constituents. "This correlation hints at a potential protective role of NRBP2 against autoimmune diseases such as RA." (PMID 40645931, 2025). "Furthermore, NRBP2 knockdown results in activation of innate immune response, which is partially dependent on L1, and NRBP2 expression level displays a negative correlation with rheumatoid arthritis (RA) autoimmune disease." (PMID 40645931, 2025). "However, our correlation analysis indicates a negative correlation between NRBP2 with occurrence of autoimmune diseases, and this should be further validated in cellular models better suited for studying immune responses and in clinically relevant samples." (PMID 40645931, 2025).
breast tumor (1 paper, 2021). "Alternatively, we also performed IHC staining of breast tumor tissues with antibodies against NRBP2, E-cadherin and N-cadherin." (PMID 33816275, 2021). "Furthermore, overexpression of NRBP2 in the orthotopic breast tumor model significantly reduced lung metastatic nodules in nude mice." (PMID 33816275, 2021).
lymph node metastasis (1 paper, 2022). "Low NRBP2 expression was linked to tumor infiltration, lymph node metastasis, and the consequent poor prognosis of patients." (PMID 35491849, 2022).
malignant brain tumors (1 paper, 2020). "We previously reported that malignant brain tumors and NSPCs share a common transcriptional signature, and selected the pseudokinase nuclear receptor binding protein 2 (NRBP2) for further study because of its high level of regulation during differentiation of NSPCs." (PMID 32517178, 2020).
ovarian carcinoma (1 paper, 2021). A malignant neoplasm originating from the surface ovarian epithelium. "Particularly, we examined if ANPEP (from EC2), CASP14 and CLEC2B (from EC3), CADM3 and NRBP2 (from EC4), and SPC25, ESCO2, and GTSE1 (from EC5) are responsible for ovarian cancer cell proliferation by the cell viability assay." (PMID 34459128, 2021). "Additionally, our study identified a number of novel markers, such as CASP14, CLEC2B, CADM3, NRBP2, SPC25, ESCO2, and GTSE1, which are upregulated in a cluster‐specific manner and critical for ovarian cancer cell proliferation and migration." (PMID 34459128, 2021).
Verheij syndrome (1 paper, 2018). "Verheij syndrome is a rare microdeletion syndrome of chromosome 8q24.3 that harbors PUF60, SCRIB, and NRBP2 genes." (PMID 30352594, 2018).
tumor (8 papers, 2019 to 2025). "In contrast, NRBP2 expression is lower in tumor tissues, and high NRBP2 expression is associated with better prognosis and chemosensitivity to sorafenib, suggesting that it serves as a tumor suppressor." (PMID 31214512, 2019). "Because this difference is highly significant, it is possible that downregulation of NRBP2 may reflect an immature, progenitor-like state of MB cells, and that loss, or reduction, of NRBP2 expression during tumor formation relates to an undifferentiated state by which MB aggressiveness increases." (PMID 32517178, 2020). "It was suggested that the NRBP2 expression is lower in tumor samples (moderate) than that in healthy samples (high)." (PMID 35491849, 2022). "In conclusion, this study reports that GATA1 can recruit HDAC2 to the NRBP2 promoter to induce its transcriptional suppression, which leads to M2 polarization of macrophages and tumor angiogenesis and development." (PMID 35491849, 2022). "IHC of tumor tissues showed that NRBP2 overexpression significantly reduced the positive staining of KI67 in the tumor tissues (oe-NC vs. oe-NRBP2: TPC-1: 43.68 vs. 21.82, p < 0.0001; CAL62: 39.51 vs. 19.74, p < 0.0001)." (PMID 35491849, 2022). "Accordingly, NRBP2 functioned as a tumor suppressor in BC, and had irreplaceable value in the control of BC progression." (PMID 33816275, 2021). "After elucidating its roles, we will obtain a better understanding of the tumor suppressor properties of NRBP2 and lay a theoretical foundation for NRBP2 to become a potential emerging therapeutic target for tumor treatment." (PMID 33816275, 2021). "Based on emerging evidence, NRBP2 participates in the progression of various tumors by inhibiting the proliferation and metastasis of tumor cells and promoting tumor cell apoptosis." (PMID 33816275, 2021). "Data from the three different websites were consistent with the conclusion that NRBP2 is expressed at significantly higher levels in normal tissues than in tumor tissues." (PMID 33816275, 2021). "NRBP2 has a 59% amino acid sequence similarity to nuclear receptor binding protein 1 (NRBP1) a pseudokinase identified as a tumor suppressor and needed for terminal differentiation of intestinal progenitor cells." (PMID 32517178, 2020). "There is little prior information to place NRBP2 in signaling networks of importance for tumor development, due to the limited published information about this group of pseudokinases." (PMID 32517178, 2020). "Overexpressing NRBP2 in MB cells shows its capacity to regulate tumor cell responses, such as reducing migration, invasion, and, most strikingly, cell numbers." (PMID 32517178, 2020). "Taken together our data indicate that downregulation of NRBP2 is a feature of MB contributing to tumor fitness." (PMID 32517178, 2020). "In addition, numerus recent works suggested regulatory roles of human NRBP1 and NRBP2 in tumor biology, as either tumor suppressor or activator." (PMID 40645931, 2025). "In addition, NRBP2 is suggested as a tumor suppressor by suppressing key oncogenic signaling pathways, such as AKT and Mammalian Target of Rapamycin (mTOR) pathways." (PMID 40645931, 2025). "They further illustrated that the anti-tumor effect of NRBP2 may be mediated by the AMPK/mTOR pathway." (PMID 38778371, 2024). "Nuclear receptor binding protein 2 (NRBP2) has been suggested as a tumor suppressor." (PMID 35491849, 2022). "Decreased NRBP2 expression was detected in TC tumor tissues and cells." (PMID 35491849, 2022). "RT-qPCR results suggested that the GATA1 expression was elevated in the collected tumor tissues versus the adjacent tissues (adjacent tissue vs. tumor: 2.14 vs. 4.80, p < 0.0001), which showed an inverse correlation with NRBP2 expression (r = −0.2674, p = 0.0241)." (PMID 35491849, 2022). "Based on these results, NRBP2 expression was downregulated in BC tumor tissues, and the decrease in NRBP2 expression might be a factor correlated with a poor prognosis of BC." (PMID 33816275, 2021).
tumor (continued). "During tumor progression, NRBP2 is consistently regarded as a tumor suppressor gene." (PMID 33816275, 2021). "Conversely, mTOR-specific inhibitors eliminated the effects of NRBP2 knockdown on increasing cell proliferation, invasion and the EMT, which suggested the anti-tumor effect of NRBP2, which may be partially related to the regulation of the AMPK/mTOR pathway." (PMID 33816275, 2021). "It was found that NRBP2 expression showed no significant relevance to the tumor size, sex, age, patients, or the histological type, whereas poor expression of NRBP2 in patients was linked to increased infiltration depth, lymph node metastasis, poor tumor differentiation, and ACR TI-RADS scores." (PMID 35491849, 2022). "After that, we examined the expression of NRBP2 mRNA in the 71 included patients using RT-qPCR and confirmed that NRBP2 was expressed at low levels in the tumor tissues versus the adjacent tissues (adjacent tissue vs. tumor: 9.55 vs. 3.44 (all mean values, the same below); p < 0.0001)." (PMID 35491849, 2022). "NRBP2 shows a 59% amino acid similarity to NRBP1 which has been identified to regulate intestinal progenitor cell homeostasis and suppress tumor formation." (PMID 35491849, 2022). "This study reports that GATA1- and HDAC2-mediated NRBP2 downregulation induced TME and angiogenesis in TC cells in vitro and tumor growth and macrophage infiltration in vivo." (PMID 35491849, 2022).
cancer (5 papers, 2019 to 2024). A tumor composed of atypical neoplastic, often pleomorphic cells that invade other tissues. "The data in TCGA-THCA suggested that the GATA1 expression was inversely correlated with the NRBP2 expression in normal tissues, cancer tissues, and THCA tissues." (PMID 35491849, 2022). "By analyzing bioinformatic tools including GSE165724 dataset and the Cancer Genome Atlas system, we predicted NRBP2 as a poorly expressed gene in TC." (PMID 35491849, 2022). "It was noteworthy that NRBP2 upregulation in cancer cells significantly decreased the number of tubes formed by HUVECs (oe-NC vs. oe-NRBP2: TPC-1: 0.36 vs. 0.12, p < 0.0001; CAL62: 0.24 vs. 0.09, p = 0.0003)." (PMID 35491849, 2022). "Cox-proportional hazard ratios on Tdark kinases and their CNAs reveal that SBK2, ETNK2, PSKH2, SCYL3, and NRBP2 are all significantly prognostic for survival across all cancers." (PMID 33205077, 2020). "Regarding NRBP2, its overexpression has been shown to be related to the inhibition of self-renewal processes in carcinoma cells." (PMID 31009519, 2019). "Likewise, decreased protein levels of NRBP2 were detected in cancer cells (Nthy-ori-3-1 vs. BCPAP/TPC-1/CAL62/SW579: 0.68 vs. 0.34/0.19/0.21/0.31; all p < 0.0001)." (PMID 35491849, 2022). "The colony formation assays also suggested that less colonies were formed by cancer cells in the setting of NRBP2 overexpression when the same number of cells were plated (oe-NC vs. oe-NRBP2: TPC-1: 213.41 vs. 132.58, p = 0.0007; CAL62 = 185.27 vs. 18.31, p = 0.0013)." (PMID 35491849, 2022). "Moreover, the immunofluorescence staining indicated that overexpression of NRBP2 in cancer cells significantly reduced the fluorescence intensity of Arg1 in the macrophages (oe-NC vs. oe-NRBP2: TPC-1: 49.31 vs. 18.42, p < 0.0001; CAL62: 42.16 vs. 13.76, p < 0.0001)." (PMID 35491849, 2022).
infection (1 paper, 2020). The state of being infected such as from the introduction of a foreign agent such as serum, vaccine, antigenic substance or organism. "The nuclear receptor binding protein, NRBP2, fights the infection of intracellular pathogens by regulating autophagy in the innate immune response." (PMID 33255903, 2020).
NRBP2 also shares sentences with these, for which no sentence is quoted: dilated cardiomyopathy (1 paper); gastric cancer (1); glioblastoma (1); heart failure (1); rheumatoid arthritis (1).